U3 (Small nucleolar RNA U3 )
Synonyms: LOC124906195
Gene: Small nucleolar RNA gene on chromosome 2 (75,627,950 to 75,628,168, forward strand). Ensembl gene ENSG00000221638.
Gene Ontology:
Biological process: RNA processing
Cellular component: nucleolus
Homologues: Orthologues: chimpanzee U3 (99% identical), macaque U3 (82% identical). Paralogues in human: U3 (61% identical), SNORD3D (60% identical), SNORD3E (60% identical), SNORD3G (60% identical), U3 (60% identical), U3 (59% identical), SNORD3P1 (59% identical), U3 (58% identical), U3 (57% identical), U3 (56% identical), SNORD3H (55% identical), U3 (55% identical), and 7 more.